MTOR (mechanistic target of rapamycin kinase)
Diseases named in the same sentence as MTOR in open-access papers (continued):
Sharing a sentence is not in itself a finding about the gene and the disease.
cancer (continued). "Studies from other groups have shown that many other signaling pathways are also involved in the regulation of cancer cell apoptosis mediated by baicalein and baicalin, including PI3K/AKT, mTOR and NF-kb signaling pathways." (PMID 29732005, 2018). "Interaction of this pathway has been demonstrated with PIM kinases in different cancers, for example, efficiency of triple inhibition of PIM, PI3K and mTOR in mantle cell lymphoma and multiple myeloma." (PMID 29401696, 2018). "The known mechanism of its anti-cancer activity is through inhibition of hedgehog, VEGFR2, Wnt, and mTOR pathways." (PMID 29930379, 2018). "The hyperactivation of two major signalling pathways, PI3K/AKT/mTOR and Ras/MAPK/MNK, occurs in the majority of the cancers and eIF4E acts as a convergence point for both signalling pathways to promote tumorigenesis." (PMID 29568373, 2018). "mTOR inhibitor (rapamycin) and the AMPK activator 5-aminoimidazole-4-carboxamide (AICA)-riboside (AICAR) are currently used separately to treat cancer patients." (PMID 30250638, 2018). "Binding of insulin-like growth factor-I (IGF-1) to its receptor (IGF-1R) initiates downstream signals that activate PI3K/Akt/mTOR and MEK/Erk pathways, which stimulate cancer cell proliferation and induce drug resistance." (PMID 29843755, 2018). "UBTOR depletion activates mTOR signaling and promotes cell growth, whilst UBTOR overexpression suppresses colony formation in cancer cell lines." (PMID 30080879, 2018). "To date, pharmacological induction of autophagy through mTOR inhibition or AMPK activation has been shown to have some therapeutic and prevention potential in cancer." (PMID 29329237, 2018). "Tumor suppressor factors are negatively regulated by mTOR and AMPK, resulting in the induction of autophagy and suppression of the cancer initiation." (PMID 30400561, 2018). "It has been demonstrated that AMPK inhibits the mammalian target of rapamycin (mTOR) and lowers HKII levels in cancer pre-clinical models." (PMID 29423101, 2018). "The PI3K/AKT/MTOR and RAF/MEK/ERK pathways are important therapeutic targets in cancer and therefore there are numerous clinically important small molecule inhibitors available to examine their function." (PMID 29329780, 2018). "Activation of the PI3K/Akt pathway, a major upstream activator of mTOR, is restrained by the lipid phosphatase and tumor suppressor PTEN (phosphatase and tensin homolog), frequently inactivated in cancer." (PMID 30147674, 2018). "We recently reported that oncogenic RAS (K-RASG13D and H-RASG12V), via its PI3K/AKT/mTOR/CK1α effector pathway, downregulates FOXO3A protein abundance in human cancer cells." (PMID 28945225, 2018). "This review highlights the role of mTOR signaling in the characterization and the activity of the TME’s elements and their implications in cancer immunotherapy." (PMID 30126252, 2018). "Previous studies have also indicated that TSN inhibited the growth of cancer cells through CDKs/cyclin, p38/JNK and mTOR/p70S6K." (PMID 30213025, 2018). "The main target of Akt is mammalian target of rapamycin (mTOR), which has a central role in PI3K-Akt pathway and cancer disease." (PMID 30166456, 2018). "The mTOR protein is a key kinase downstream of the PI3K/AKT proteins, which regulate cancer cell proliferation, growth, survival, and angiogenesis." (PMID 29875348, 2018). "EGFR is involved in Jak/STAT, nfb, mTOR and MAPK signaling pathways, thereby influencing cancer cell self-renewal, proliferation, differentiation and migration." (PMID 30587839, 2018).
cancer (continued). "It has been elucidated that GOLPH3 can regulate cell size, enhance growth-factor-induced mTOR signaling in many human cancer cell lines like A549 and CRL-5889, and alter the response to rapamycin which is a mTOR inhibitor in vivo." (PMID 29914442, 2018). "PI3Ks in combination with protein kinase B (AKT) and mTOR (mammalian target of rapamycin) also known as the PI3K/AKT signalling pathway is crucial to many aspects of cell growth/survival and apoptosis, and subsequently cancer." (PMID 29755656, 2018). "Several FDA-approved anti-cancer therapies were identified, including the RXRA agonist bexarotene and mTOR inhibitors, such as everolimus." (PMID 30176882, 2018). "Slightly fewer proteins (10.8%) were uniquely bimodal only at the protein level, including important cancer-related proteins such as MEK1, mTOR, E2F1, TTF1, EIF4G, and JAB1." (PMID 29293502, 2018). "Treatment of HPV-positive cancer cells with mTOR inhibitors released them from HPV oncoprotein “addiction,” thus, enabled the escape of cancer cells from senescence when E6/E7 expression is blocked." (PMID 29637045, 2018). "Because eIF4E phosphorylation resides at a convergent point between two predominant signaling pathways (mTOR and ERK signaling), the MKNK kinases play a critical role in the downstream translation initiation of pro-cancer mRNA." (PMID 29568395, 2018). "Accordingly, the stimulation of the PI3K/AKT/mTOR pathway by insulin facilitated the normoxic stabilization of hypoxic inducible factor 1 (HIF1), thereby increasing PKM2 expression to promote cancer type metabolism." (PMID 29468140, 2018). "mTOR regulation by PIM kinases and their interrelation in other cancers advocate their magnitude in tumorigenesis." (PMID 29401696, 2018). "In addition, to test a hypothesis that mTOR complexes are a key node to integrate growth factor receptor signaling with nutrient availability, influencing tumor growth and response to treatment, it will be necessary to study the role of mTOR and its modulation by nutrients in various cancer types." (PMID 30347859, 2018). "In cancer cells, PI3K/AKT activity is increased which activates mTOR complex via phosphorylation and decreases the feedback activation of p70S6k1/mTOR complex." (PMID 30096805, 2018). "In this study, we found stromal cell-derived SPINK1 not only activates Akt/mTOR, Mek/Erk/Stat3 pathways, signaling branches downstream of EGFR, but also generates profound impact on cancer cell transcriptomics." (PMID 30333494, 2018). "Both the phosphatidylinositol-3-kinase (PI3K)/AKT/mammalian target of rapamycin (mTOR), and the mitogen-activated protein kinase (MAPK) pathways are important in normal cell function and cancer cell biology." (PMID 30287915, 2018). "In cancer cells, AKT/mTOR pathway controls cellular autophagy, therefore, we tested the effects of serotonin on AKT/mTOR signaling and autophagy." (PMID 30409162, 2018). "Rapamycin/crizotinib co-treatment was well tolerated, which is in line with recent pre-clinical studies in MPM and other cancers when crizotinib and PI3K/mTOR inhibitors were applied." (PMID 29755689, 2018). "Targeting those proteins led to the development of cancer therapeutics such as erlotinib and gefitinib (EGFR inhibitors), LY294002 (PI3K inhibitor), peritosine (Akt inhibitor), rapamycin and sirolimus (mTOR inhibitors), and many others." (PMID 29713280, 2018). "mTOR is an attractive target for cancer therapy, because the activation of phosphoinositide 3-kinase (PI3K)-mTOR signaling promotes resistance to conventional chemotherapies." (PMID 29423269, 2018). "In summary, our results show that EBV-miR-BART1-5P has important roles in cancer cell glucose metabolism and angiogenesis by inhibiting AMPKα1, which provides a molecular basis for the regulation of AMPK/mTOR/HIF1 pathway." (PMID 30557400, 2018).
cancer (continued). "Cancer cells that survived after initial cycles acquire resistance through multiple cellular mechanisms such as activation of NF-κB, PI3K, Akt, and mTOR but the resistance to radiotherapy in GBM is primarily attributed to EGFRvIII." (PMID 29651429, 2018). "Various mTOR inhibitors are in ongoing clinical trials and the FDA-approved rapalog everolimus is used in various cancer cell types." (PMID 29662490, 2018). "A recent report claimed that the combined blockage of Akt/mTOR and MDM2 augments cell apoptosis and differentiation in GBM cancer stem cells." (PMID 29769662, 2018). "It is well documented that the PI3K/Akt/mTOR and TGF-β/Smad signaling pathways are becoming increasingly difficult to ignore in investigations of EMT-related mechanisms in cancer cells." (PMID 29882900, 2018). "Accordingly, mTOR inhibitors are only FDA- and EMA-approved for use in patients with a few types of cancer, such as mantle cell lymphoma, pancreatic neuroendocrine tumors, advanced renal cell carcinoma, and giant cell astrocytoma." (PMID 28616837, 2018). "By activating the AKT/mTOR signal, ANRIL upregulates GLUT1 and LDHA expression, thus increasing glucose uptake and promoting cancer progression in NPC cells." (PMID 30134946, 2018). "TCGA identified pan-cancer driver pathways: multiple RTKs; proliferation and growth (Ras/Raf/MEK/ERK; PI-3K/PTEN/AKT/mTOR); cell cycle; DNA damage." (PMID 29579036, 2018). "PTEN (gene, mRNA, and protein) status was extensively characterized in a panel of cancer cell lines and combined MEK/mTOR inhibition displayed highly synergistic pharmacologic interactions almost exclusively in PTEN-loss models." (PMID 28220839, 2017). "The AKT/mTOR and JNK pathways play vital roles in regulating proliferation and metastasis in many cancers." (PMID 29078789, 2017). "For effective cancer therapy, PI3K inhibitors in combination with pathways targeting Akt, mTOR, RTKs (receptor tyrosine kinases), MAPK (mitogen activated protein kinase), EGFR (epidermal growth factor receptor), HER2 (human EGF receptor 2), DNA repair enzymes." (PMID 29311925, 2017). "Several recent studies also show that the combination of mTOR and HDAC inhibitors exert a synergistic antitumor activity in a large panel of human cancer cell lines, and the patient-derived xenograft and transgenic mouse models." (PMID 29263324, 2017). "Considering the many functions of mTOR, such as sensing metabolic changes, these results and studies implicate HSF1 in many functions of cancer cell biology and a significant interplay between PI3K/AKT signaling, mTOR signaling, and HSF1 activity." (PMID 29088759, 2017). "Many mTOR pathway inhibitors have entered the clinics and metformin, a AMPK activator has potential both in cancer therapy and healthy aging." (PMID 28966806, 2017). "Currently combinations of mTOR- and MAPK-pathway inhibitors are being tested for the treatment of cancer." (PMID 28562352, 2017). "Metformin inhibits the cell growth of various cancers alone or in combination with other therapeutic agents via LKB1-dependent or LKB1-independent activation of AMPK and subsequent suppression of mTOR and its downstream effectors." (PMID 29228674, 2017). "Different molecular mechanisms for the action of flavonoids on cancer cells have been proposed, including induction of apoptosis, generation of ROS, and signaling mediated via the MAPK and Akt–mTOR pathways." (PMID 28703746, 2017). "Severely decreased ECHS1, accumulation of BCAAs and FAs, activation of mTOR and overexpression of BCL-2 were observed in cancer tissues from metabolic organs." (PMID 28878358, 2017).
cancer (continued). "Like the metabolic regulation in cancer cells, the change in T cell metabolism relies on a hierarchical signaling cascade involving PI3K/Akt, AMP-activated protein kinase (AMPK)/mTOR and MAPK." (PMID 28245597, 2017). "Second, we tested the efficacies of an mTOR inhibitor (Torin 1), a mitogen-activated protein kinase (MAPK) inhibitor (PD98059) and a neutralizing antibody against E-cadherin on cancer cells in BICA, IVBL or 2D cultures." (PMID 28429794, 2017). "Our discovery of drugs with a dual-inhibitory mechanism provides a unique pharmacological strategy against cancer and evidence of cross-activation between the Ras/Raf/MEK/ERK and PI3K/AKT/mTOR pathways via a Ras˧PIK3IP1˧PI3K signaling network." (PMID 29259156, 2017). "In cancer cells, AMPK activation by metformin has been shown to inhibit the mTOR pathway, global protein synthesis and proliferation in numerous different cancer cell lines." (PMID 28157701, 2017). "Hyperactivated oncogenic pathways, including the AKT/mTOR and JNK pathways, are important drivers of the malignant transformation of cancer cells." (PMID 29078789, 2017). "Preclinical studies suggest that GSK2126458 inhibits proliferation of a variety of cancer cell lines and tumours in xenograft mouse models with induction of apoptosis and attenuation of the PI3K/Akt/mTOR activity." (PMID 28938574, 2017). "Collectively, these data argue that the hypoxic impairment of mTOR signaling, which occurs at least in part via the inhibitory REDD1/TSC2 axis, enables HPV-positive cancer cells to evade senescence under conditions of E6/E7 repression." (PMID 28678198, 2017). "Blocking REDD1 or TSC2 expression by RNAi leads to the stimulation of mTOR signaling and to the emergence of senescent HPV-positive cancer cells under hypoxia." (PMID 28678198, 2017). "In many cancers the PI3K-AKT and RAS-MAPK signaling pathways are deregulated and both pathways converge on mTOR signaling." (PMID 28484242, 2017). "We also found that DEK promoted cancer cell angiogenesis and metastasis by activating the PI3K/AKT/mTOR pathway." (PMID 29228721, 2017). "The mTOR and ERK1/2 pathways both importantly participated in the process of autophagy occurred in various cancer cell types." (PMID 28675698, 2017). "Activation of mTOR signaling by feeding induced a clear mobility shift in DEPTOR protein levels, confirming that the protein is subject to a similar regulation in cancer cells and in normal tissues." (PMID 28462079, 2017). "Mammalian target of rapamycin (mTOR) is a well-established oncogenic pathway and therapeutic target for HCC and many other cancers." (PMID 28334043, 2017). "Recently, it was demonstrated that NRP2 regulates mTOR signaling, β-catenin signaling, endosome maturation, and EGFR trafficking sustaining cancer development." (PMID 28804523, 2017). "Higher concentration of Cur kills cancer cells and can be used to treat different cancers, by generating ROS and disrupting AKT/mTOR signaling, inducing apoptotic death, inhibiting NF-κB in human neuroblastoma." (PMID 29359011, 2017). "PTEN inactivation occurs commonly in human cancers and putatively activates the PI3K/AKT/ mTOR pathway." (PMID 29156674, 2017). "These pathways, including mTOR Signaling, Cell Cycle G1/S Checkpoint, Wnt Signaling, AMPK signaling, and ERK/MAPK Signaling, were all critical for cancer development and progression." (PMID 28947992, 2017). "In the study, by mining the Cancer Cell Line Encyclopedia (CCLE) database, we found that PI3K/AKT/mTOR pathway was aberrant in 92% of SCLC cell lines." (PMID 29290965, 2017).
cancer (continued). "The aberrant activation of PI3K-AKT-mTOR signaling induces the overexpression of HIF-1 in cancer, and the dual PI3K/mTOR inhibitor, NVP-BEZ235, suppresses hypoxia-induced HIF-1 expression and enhances apoptosis of cancer cells under hypoxic stress." (PMID 28841148, 2017). "In particular, dual inhibition of PI3K and mTOR has been considered an effective strategy for cancer therapy, since it directly targets the most common PI3K mutants and suppresses PI3K-independent activation of mTOR." (PMID 29296217, 2017). "miR-223 has been found to affect the cell cycle by regulating E2F1 35, migration and invasion in cancer cells by targeting EPB41L3 36, proliferation and tumor growth of cells by targeting IGF1R and downstream Akt/mTOR/p70S6K signaling pathway 37,38." (PMID 29090068, 2017). "The activation of FAK/Syk/Akt/mTOR and STAT3 pathways contributes to Reelin-induced cancer cell growth and metabolic reprogramming." (PMID 28345605, 2017). "mTOR signaling, a central regulator of cell metabolism, is frequently activated in MCL and is also an important therapeutic target in this cancer." (PMID 28388555, 2017). "The process of EMT contributes to radioresistance of cancer cells via induction of EMT-related genes/signals, such as PI3K/AKT, PTEN (phosphatase and tensin homolog), mTOR (mechanistic target of rapamycin kinase) and TGF-β, which inhibit cell death signals." (PMID 28872613, 2017). "BE had a direct effect on “Pathways in cancer”, by significantly down-regulating genes involved in cytokine–cytokine receptor interaction, MAPK signaling pathway and mTOR signaling pathway." (PMID 28359318, 2017). "Activation of ErbB2 downstream signaling pathways PI3K/AKT/mTOR and Ras/Raf/MEK/ERK contributes to trastuzumab resistance in ErbB2‐positive cancer cells." (PMID 28781955, 2017). "Western blot analysis showed that multiple components in the EGFR-Akt-mTOR pathway were clearly affected by cell density in both HCT116 and CNE-2Z cancer cell lines." (PMID 28061454, 2017). "miRNAs can influence cancer proliferation and metastasis through multiple pathways, such as the AKT/mTOR and JNK pathways." (PMID 29078789, 2017). "The PI3K/AKT/mTOR and MEK/ERK pathways are two of the most commonly aberrantly activated pathways in human cancers." (PMID 28423521, 2017). "mTOR and class I PI3K are two major and interdependent oncogenic kinases that contribute to cancer biology through the synthesis of cellular components and the regulation of growth, proliferation, migration, survival, and angiogenesis." (PMID 28423515, 2017). "Specifically, cancer cells classified as expressing the survival phenotype were sensitive to therapies that target AKT, PI3K, HER2, and mTOR." (PMID 28446242, 2017). "By signaling through its receptor (LEP-R), which is upregulated in certain cancers, leptin can activate the PI3K/Akt/mTOR and Janus kinase/signal transducer and activator of transcription (JAK/STAT) pathways." (PMID 28959684, 2017). "Therefore, the clinical significance of p-mTOR expression in different cancers remains unclear." (PMID 28114374, 2017). "Here we show that PARK2 is altered in over a third of all human cancers, and its depletion results in enhanced phosphatidylinositol 3-kinase/Akt (PI3K/Akt) activation and increased vulnerability to PI3K/Akt/mTOR inhibitors." (PMID 28306514, 2017). "Our results suggest that the mTOR pathway may link metabolic stress with DNA damage responses to control cell cycle progression and survival in response to the ever-changing availability of nutrients, growth factors and oxygen from the microenviroment of cancer cells that lead to DNA damage." (PMID 28484242, 2017).